RNF138 (ring finger protein 138)
Description:
E3 ubiquitin-protein ligase involved in DNA damage response by promoting DNA resection and homologous recombination. Recruited to sites of double-strand breaks following DNA damage and specifically promotes double-strand break repair via homologous recombination. Two different, non-exclusive, mechanisms have been proposed. According to a report, regulates the choice of double-strand break repair by favoring homologous recombination over non-homologous end joining (NHEJ): acts by mediating ubiquitination of XRCC5/Ku80, leading to remove the Ku complex from DNA breaks, thereby promoting homologous recombination. According to another report, cooperates with UBE2Ds E2 ubiquitin ligases (UBE2D1, UBE2D2, UBE2D3 or UBE2D4) to promote homologous recombination by mediating ubiquitination of RBBP8/CtIP. Together with NLK, involved in the ubiquitination and degradation of TCF/LEF. Also exhibits auto-ubiquitination activity in combination with UBE2K. May act as a negative regulator in the Wnt/beta-catenin-mediated signaling pathway.
Synonyms: hNARF; NARF; HSD-4; STRIN
Tractability: PROTAC: UniProt records ubiquitination sites on it; ubiquitination databases record sites on it.
Gene: Protein-coding gene on chromosome 18 (32,091,871 to 32,131,561, forward strand). Ensembl gene ENSG00000134758.
Subcellular location: Chromosome
Subcellular location (Human Protein Atlas): Mitochondria
Pathways (Reactome):
Immune System: Antigen processing: Ubiquitination & Proteasome degradation
Gene Ontology:
Molecular function: protein binding; protein kinase binding; single-stranded DNA binding; ubiquitin protein ligase activity
Biological process: DNA double-strand break processing involved in repair via single-strand annealing; double-strand break repair via homologous recombination; protein ubiquitination
Cellular component: chromosome; nucleus; site of double-strand break
Genetic constraint (gnomAD): Loss-of-function variants: 2 observed, 6.99 expected, observed/expected ratio (o/e) 0.29, 90% interval 0.12 to 0.9. That is too few expected variants to judge how well the gene tolerates losing a copy. Missense variants: 77 observed, 103.33 expected, observed/expected ratio (o/e) 0.75, 90% interval 0.62 to 0.9. Synonymous variants: 57 observed, 39.04 expected, observed/expected ratio (o/e) 1.46, 90% interval 1.18 to 1.81.
Homologues: Orthologues: chimpanzee RNF138 (100% identical), macaque RNF138 (99% identical), pig RNF138 (99% identical), rabbit RNF138 (98% identical), guinea pig RNF138 (97% identical), mouse Rnf138 (94% identical), dog RNF138 (93% identical), rat AABR07031480.1 (92% identical), tropical clawed frog rnf138 (48% identical). Paralogues in human: RNF166 (31% identical), RNF114 (28% identical), RNF125 (27% identical), RNF180 (17% identical).
Diseases named in the same sentence as RNF138 in open-access papers:
RNF138 is named in the same sentence as 15 diseases in open-access papers, as found by Europe PMC text mining. Sharing a sentence is not in itself a finding about the gene and the disease. The quoted sentences say what the papers report.
glioblastoma (4 papers, 2018 to 2023). The most malignant astrocytic tumor (WHO grade IV). "Recent studies have demonstrated that RNF135 and RNF138 amplification activate the ERK signaling pathway in glioblastoma, which promotes cellular proliferation, migration, and invasion." (PMID 34081837, 2021). "In highly malignant glioblastomas, the E3 ubiquitin ligase RNF138 has been shown to mediate ribosomal protein S3 (rpS3) ubiquitination, thereby inhibiting rpS3/DDIT3-mediated apoptotic signaling when stimulated by radiation and inducing radioresistance in glioblastoma (GBM) cells." (PMID 38137461, 2023). "For example, RNF138 induces ubiquitin-dependent degradation of RPS3 and subsequently leads to radioresistance in glioblastoma (GBM) cells." (PMID 36567344, 2023).
glioma (3 papers, 2019 to 2022). A benign or malignant brain and spinal cord tumor that arises from glial cells (astrocytes, oligodendrocytes, ependymal cells). "The EMT in glioma tissues is correlated with high expression of ring finger protein 138 (RNF138), which regulates caspase 3, E-cadherin, p-ERK1/2, vimentin, MPP-2, HIF-1α, and VEGF." (PMID 31200510, 2019). "Downregulation of RNF138 inhibits EMT in glioma cells via suppression of the ERK/MAPK signaling." (PMID 31988090, 2020).
gastric cancer (2 papers, 2018 to 2021). A primary or metastatic malignant neoplasm involving the stomach. "RNF138 was more highly expressed in cisplatin-resistant gastric cancer (GC) cell lines than in normal cell lines and modulated cisplatin resistance in these GC cells." (PMID 33935743, 2021).
Chronic colitis (1 paper, 2022). A chronic inflammatory disease of the large intestine (colon, cecum and rectum). "Thus, we propose that RNF138 suppresses the chronic colitis switch to colonic neoplastic transformation." (PMID 35697692, 2022).
colitis (1 paper, 2022). Inflammation of the colon. "RNF138−/− mice were hyper-susceptible to the switch from colitis to aggressive malignancy, which coincided with sustained aberrant NF-кB signaling in the colonic cells." (PMID 35697692, 2022). "We systematically examined the global changes imposed by RNF138 deficiency in either the colon tissues dissected from the colitis and CAC models or the organoids derived from the CAC model." (PMID 35697692, 2022). "Thus, RNF138 is functionally linked to the NF-κB signaling that is critical for a cascade of events from the onset of colitis to the colitis-to-tumor transition and further CAC tumor progression." (PMID 35697692, 2022). "Further investigation revealed that deficient RNF138 led to the dysregulation of NF-κB signaling that significantly promotes the colitis switch to malignancy, which can be effectively suppressed with specific inhibitors against individual components of the pathway." (PMID 35697692, 2022). "Upon the colitis occurrence, RNF138−/− mice deteriorated more rapidly than RNF138fl/fl mice under co-housing condition, which was reflected in both the change in clinical scores and weight loss, and ultimately suffered a higher mortality rate." (PMID 35697692, 2022). "We demonstrated that downregulation of RNF138 significantly promoted the transition from colitis to tumor and sensitized the CRC cells to SC75741, a highly potent and specific NF-κB signaling inhibitor." (PMID 35697692, 2022). "Using the ex vivo colitis and CAC models, we confirmed that RNF138 functions as a suppressor of CRC tumorigenesis through preventing excessive activation of NF-κB signaling." (PMID 35697692, 2022).
Splenomegaly (1 paper, 2022). Abnormal increased size of the spleen. "The colorectum in RNF138−/− mice were significantly reduced in length and exhibited splenomegaly as opposed to the control." (PMID 35697692, 2022).
cancer (4 papers, 2012 to 2025). A tumor composed of atypical neoplastic, often pleomorphic cells that invade other tissues. "Low expression of RNF138 was significantly associated with resistance of cancer cells to Quizartinib (P value = 3.03E-11)." (PMID 33281885, 2020). "This insight suggests that RNF138 could serve as a potential therapeutic target in diseases where Wnt signaling is dysregulated, such as cancers and degenerative disorders." (PMID 40225576, 2025). "These 58 predicted target mRNAs included many genes previously reported to be involved in tumorigenesis of CRC or other malignant tumors such as KLF4, SFRP1, SFRP2, RNF138." (PMID 22703586, 2012).
tumor (2 papers, 2018 to 2022). "SC75741 appeared effective in suppressing CRC tumor cell growth by the NF-κB pathway, and could restore the aberrant NF-κB signaling with deficient RNF138-NIBP axis." (PMID 35697692, 2022). "We constructed the tumor organoids system to understand RNF138’s role in the CRC tumorigenesis and progression, in which the growth of organoids was monitored for 9 days from day 0.5 post transplantation." (PMID 35697692, 2022). "Furthermore, we found that both the tumor number and tumor load were nearly doubled in the RNF138−/− mice along with significant increase in size." (PMID 35697692, 2022). "Using the xenograft models built upon either RNF138-dificient CRC cells or the cells derived from the RNF138-dysregulated CRC patients, we demonstrated that the inhibition of NF-кB signaling effectively hampered tumor growth." (PMID 35697692, 2022). "Altogether, these results confirmed that RNF138 suppresses the tumor growth independent of the orthotopic microenvironment." (PMID 35697692, 2022).
RNF138 also shares sentences with these, for which no sentence is quoted: ataxia telangiectasia (1 paper); Cachexia (1); cholangiocarcinoma (1); Crohn disease (1); episodic ataxia type 2 (1); head and neck squamous cell carcinoma (1); thyroid carcinoma (1).